IL19 (interleukin 19)
Diseases named in the same sentence as IL19 in open-access papers (continued):
Sharing a sentence is not in itself a finding about the gene and the disease.
atopic dermatitis (7 papers, 2019 to 2023). "Increased IL-19 expression is usually observed in inflammatory skin, such as atopic dermatitis and aging." (PMID 36476273, 2022). "In light of these data, we extended our analyses to atopic dermatitis, a second, common, chronic inflammatory skin disease, by examining IL-19 levels in patients enrolled in a phase 2 study for the JAK1/2 inhibitor baricitinib." (PMID 30914699, 2019). "In atopic dermatitis, IL-19 was significantly elevated, correlated with EASI scores, and decreased with skin improvement." (PMID 30914699, 2019). "We found that in atopic dermatitis, serum IL-19 was markedly elevated, was highly correlated with EASI, and served as a leading biomarker for skin improvement." (PMID 30914699, 2019). "Skin biopsy specimens from Asian children with atopic dermatitis express significantly higher levels of T helper Th17‐ and Th22‐related cytokines (especially interleukin (IL)‐17A, IL‐19, and IL‐22) and IL‐17/IL‐22 than found in skin biopsy specimens from European American children." (PMID 36705040, 2023). "We also measured IL-19 in baricitinib-treated atopic dermatitis patients." (PMID 30914699, 2019).
Arthritis (6 papers, 2014 to 2024). Inflammation of a joint. "Recent studies demonstrated that blocking of IL-19 or IL-20 reduced bone loss and ameliorated collagen-induced arthritis in rat, suggesting that IL-19 and IL-20 are important proinflammatory molecules in bone or joint related diseases." (PMID 30250404, 2018). "Antibodies targeting IL-19 have prevented arthritis and osteolysis in animal models by diminishing the secretion of pro-inflammatory cytokines, including TNF-α, IL-1β, IL-6, and RANKL." (PMID 39104791, 2024). "A recent study showed that a broad blockade of IL-20 subfamily (including IL-19, IL-20, and IL-24) by using soluble-IL-20R2-Fc fusion protein significantly ameliorated the severity of arthritis in CIA model." (PMID 29690863, 2018). "In the context of arthritis, it is intriguing that IL-20 has also been reported as a driver of osteoporosis and that both IL-19 and IL-24 had roles in a rat model of bone resorption." (PMID 26968800, 2016). "Expression of IL-19, IL-20, and IL-24 in both monocytes/macrophages and fibroblast-like synovial cells has been reported in arthritis." (PMID 26968800, 2016). "IL-19 seems to have anti-inflammatory functions in arthritis." (PMID 30319661, 2018). "As a member of IL-20 subfamily, IL-19 was also overexpressed in CIA rat model, and treatment of anti-IL-19 antibody significantly ameliorated the severity of arthritis." (PMID 29690863, 2018).
COVID-19 (6 papers, 2021 to 2024). A disease caused by infection with severe acute respiratory syndrome coronavirus 2. "In this study, we show that IL-19 level is significantly increased in saliva of asymptomatic COVID-19 patients compared to healthy controls, and its level associated with COVID-19 disease severity." (PMID 36163397, 2022). "Next, we have evaluated the association between IL-19 and IL-6 levels in saliva of severe COVID-19 cases with the survival outcomes of these patients." (PMID 36163397, 2022). "Furthermore, higher IL-19 level in saliva of severe COVID-19 patients was associated with higher need for mechanical ventilation and/or death within 29 days of admission." (PMID 36163397, 2022). "Taken together, the observed increase in saliva IL-19 levels in asymptomatic COVID-19 cases compared to healthy controls, and in severe COVID-19 cases suggest the potential use of IL-19 as a non-invasive salivary diagnostic and prognostic biomarker for COVID-19 severity." (PMID 36163397, 2022). "Here, we further observed that IL-19 expression was positively correlated with IL-17 level in nasopharyngeal swabs and lung autopsies of COVID-19 patients." (PMID 36163397, 2022). "Of 202 adult COVID-19 patients, IL-19 protein level was significantly higher in blood and saliva of asymptomatic patients compared to healthy controls when adjusted for patients’ demographics (P < 0.001)." (PMID 36163397, 2022). "Our findings indicate that IL-19 is upregulated significantly in plasma and saliva of patients with COVID-19 relative to disease severity." (PMID 36163397, 2022). "This suggests that IL-19 can be utilized as a noninvasive salivary biomarker for COVID-19 infectivity and severity." (PMID 36163397, 2022). "To evaluate that, we measured the plasma IL-19 level of severe COVID-19 patients who were on corticosteroids, tocilizumab (humanized anti-IL-6 receptor antibody), or interferon-β (IFNβ) treatment." (PMID 36163397, 2022). "The level of IL-19 protein was also evaluated in the plasma and saliva of recruited COVID-19 patients with different levels of disease severity." (PMID 36163397, 2022). "The plasma and saliva levels of IL19 significantly increase in patients with severe COVID-19." (PMID 38543303, 2024). "Moreover, as expected, the level of phosphorylated STAT3 (p-STAT3), which is regulated by IL-19, was significantly upregulated in saliva of COVID-19 patients compared to healthy controls, which is suggestive of IL-19 signaling." (PMID 36163397, 2022). "In fact, STAT3 was hyperactive in saliva of COVID-19 cases suggestive of IL-19 signaling." (PMID 36163397, 2022). "Furthermore, in this study, we showed that IFNβ significantly reduced IL-19 plasma level of COVID-19 patients, while corticosteroids and tocilizumab had limited effect on IL-19." (PMID 36163397, 2022). "Herein, through the analysis of transcriptomic datasets of SARS-CoV-2 infected lung cells, nasopharyngeal swabs, and lung autopsies of COVID-19 patients, we report that expression levels of IL-19 and its receptor, IL-20R2, were upregulated following SARS-CoV-2 infection." (PMID 36163397, 2022). "Collectively, IL-19 as a component of the IL-23/IL-17 axis could strengthen the IL-17A-mediated immunopathological effect during severe COVID-19." (PMID 36163397, 2022). "The addition of IFNβ to COVID-19 antiviral regimen might block IL-19 stimulated cytokines by downregulating IL-19 and attenuating STAT3 signaling, leading to better control of cytokine storm and the associated COVID-19 hyperinflammation condition." (PMID 36163397, 2022). "Moreover, we noticed a significant increase in IL-19 plasma and saliva levels relative to COVID-19 severity." (PMID 36163397, 2022). "In addition, we correlated IL-19 level in saliva of COVID-19 patients with the serum markers of COVID-19 severity." (PMID 36163397, 2022). "However, the role of IL-19 in COVID-19 pathogenesis remains elusive." (PMID 36163397, 2022).
COVID-19 (continued). "We then determined whether IL-19 level are affected by common COVID-19 medications." (PMID 36163397, 2022). "Moreover, the value of IL-19 in saliva might help inform therapeutic interventions to determine which patients are likely to have progression of COVID-19 severity resulting in mechanical ventilation and/or death." (PMID 36163397, 2022). "Patients with severe COVID-19 have elevated plasma levels of the IL10 family of cytokines, IL19, and IL24, which decrease during recovery." (PMID 38543303, 2024). "Here, we assessed the gene expression level of IL-19 in SARS-CoV-2 infected lung cells, nasopharyngeal swabs and lung autopsies of COVID-19 patients using publically available gene expression data sets." (PMID 36163397, 2022). "Next, to test whether IL-19 level correlates with SARS-CoV-2 infectivity and COVID-19 severity, we measured IL-19 protein level in the plasma and saliva of our recruited COVID-19 patients (n = 202) and heathy controls (n = 20)." (PMID 36163397, 2022). "IL-19 expression was higher in vitro, in SARS-CoV-2 infected AECs, and in COVID-19 patients’ blood compared to influenza or RSV infections, suggesting it may represent a marker of coronavirus infection." (PMID 36163397, 2022). "To assess the level of IL-19 in the airways following SARS-CoV-2 infection, we evaluated IL-19 gene expression levels in vitro, in SARS-CoV-2 infected AECs, and in vivo, in nasopharyngeal swabs and lung autopsies of COVID-19 patients." (PMID 36163397, 2022). "On the contrary, taking into account anti-inflammatory cytokines, IL-1RA, IL-10, IL-27, and IL-19 were higher in COVID-19 pregnant women if compared with noninfected ones." (PMID 34326336, 2021). "However, the expression of IL-19 in the context of COVID-19 and relative to disease severity has never been investigated." (PMID 36163397, 2022). "Moreover, to gain better understanding of IL-19 signaling following SARS-CoV-2 infection, we examined levels of IL-19 heterodimer receptor complex, IL-20R1 and IL-20R2, in SARS-CoV-2 infected AECs, nasopharyngeal swabs and lung autopsies of COVID-19 patients." (PMID 36163397, 2022).
dermatitis (6 papers, 2021 to 2025). An inflammatory process affecting the skin. "Related to dermatitis, we found an upregulation of CD74, BTLA, TRAF2, TNIP1, and IL19." (PMID 41416938, 2025).
periodontitis (6 papers, 2015 to 2025). An acute or chronic inflammatory process that affects the tissues that surround and support the teeth. "The salivary levels of IL-19 has not previously been reported as elevated in patients with periodontitis, but we have previously reported that the gene IL-19 is significantly up-regulated in gingival tissue biopsies from patients with periodontitis compared to healthy controls." (PMID 31281801, 2019). "In addition, the levels of sTNF-R1, IL-10, and IL-19 also differed significantly between periodontitis patients and healthy individuals." (PMID 31281801, 2019). "The results revealed that three cytokines, namely glycoprotein 130 (gp130)/soluble IL-6 receptor β (sIL-6Rβ), IL-19 and soluble TNF receptor 1 (sTNF-R1), were significantly (P < 0.05) higher in periodontitis compared to controls." (PMID 31281801, 2019). "Levels of sCD30/TNFRSF8, IFN-α2, IL-19, IL-26, MMP-1, gp130/sIL-6Rß, and sTNF-R1 were significantly higher in serum or GCF, and April/TNFSF13 was significantly higher in serum and saliva samples in moderate/severe periodontitis." (PMID 31072030, 2019). "Among the detected inflammatory mediators in saliva samples, TWEAK/TNFSF12, IL-35, IFN-α2, pentraxin-3, gp130/sIL6Rb, sIL-6Ra, IL-19 and sTNF-R1 were found to be significantly increased in patients with periodontitis and RA compared to non-RA group with periodontitis." (PMID 35360114, 2022). "Our data showed that several inflammatory mediators were increased in RA-periodontitis saliva as compared to non-RA, including TWEAK/TNFSF12, pentraxin-3, IL-19, IL-35, gp130/sIL6Rb, sIL-6Ra, IFN-α2 and sTNF-R1." (PMID 35360114, 2022). "In the present study, the levels of sCD30 (TNFRSF8), sTNF-R1, gp130 (sIL-6Rß), IL-19, IL-26 and MMP-1 were increased in serum, saliva or GCF samples from subjects with moderate/severe periodontitis as compared to no/mild disease." (PMID 31072030, 2019). "In GCF samples, significantly (p < 0.05) higher levels of IFN-α2, IL-19, IL-26, MMP-1 and sTNF-R1 were observed in RA patients with moderate/severe periodontitis compared to corresponding RA subjects with no/mild periodontitis." (PMID 31072030, 2019).
Stroke (6 papers, 2018 to 2025). Sudden impairment of blood flow to a part of the brain due to occlusion or rupture of an artery to the brain. "An IL19 risk allele, rs17581834(T), was associated with both stroke and myocardial infarction in patients with SLE, but this was not lupus-specific, as it was also present in patients with RA." (PMID 40725777, 2025). "Interleukin-19 (IL-19), part of the IL-10 subfamily which includes IL-10, IL-20, IL-22, and IL-24, has been shown to be neuroprotective after stroke." (PMID 33532035, 2021). "A recent study associated an IL-19 risk allele, rs17581834 (T), with stroke/myocardial infarction in patients with SLE and RA, but not HC, implying a shared immune pathway in the pathogenesis of immune diseases and CVD72." (PMID 35680906, 2022). "A study demonstrated that the IL19 risk allele was relevant to stroke/MI in SLE and RA, but not in the general population, showing that shared immune pathways may be contained in cardiovascular disease pathogenesis and inflammatory rheumatic diseases." (PMID 37474895, 2023). "Previous studies showed that IL-19 acts in an autocrine and paracrine negative-feedback regulator to limit pro-inflammatory responses by microglia and macrophages, and that it can slow the progression of microglia/macrophage-mediated CNS disorders such as stroke and spinal cord injury." (PMID 33931083, 2021).
acne (5 papers, 2018 to 2025). An inflammatory process of the sebaceous glands which is characterized by comedones, nodules, papules and/or pustules on the skin. "Building on existing evidence, this study examines the relationship between serum and salivary levels of CRP, IL-17, and IL-19 in patients with acne vulgaris (AV), with a particular focus on their association with disease severity and scarring forms." (PMID 41465543, 2025). "Furthermore, the inflammatory process of acne is linked to cytokines such as TWEAK, IL-19, and IL-17, with IL-19 being linked to the severity of acne and suggested as a predictive inflammatory marker for typical acne." (PMID 37554505, 2023). "Another study showed that TT genotype of IL-19 might be a hereditary risk factor for acne vulgaris development, and it was associated with elevated IL-19 serum levels, which could be a marker of acne severity." (PMID 35905107, 2022). "One of these studies reported elevated IL-19 levels in patients who had received recent systemic or topical acne treatments." (PMID 41465543, 2025). "Acne vulgaris (AV) is a chronic inflammatory skin disorder, and cytokines such as interleukin-17 (IL-17), interleukin-19 (IL-19), and C-reactive protein (CRP) are thought to contribute to its immunopathogenesis." (PMID 41465543, 2025). "Our aim is to estimate the level of IL-19 in patients with AV compared to matched controls and to investigate the role of IL-19 in the pathogenesis of acne." (PMID 38106772, 2023). "The present research sought to find out the difference in IL-19 serum concentration on degrees of severity of acne vulgaris; this is the pilot study of IL-19 serum in acne vulgaris patients." (PMID 29805787, 2018). "This pilot study aims to look at difference in IL-19 serum concentration on degrees of severity of acne vulgaris." (PMID 29805787, 2018). "Analysis test found statistically significant difference between IL-19 serum concentration of group of patients with mild acne vulgaris and that of group of patients with severe acne vulgaris." (PMID 29805787, 2018). "The present research was intended to find out the difference in IL-19 serum concentration on various degrees of severity of acne vulgaris." (PMID 29805787, 2018). "The present research detected proportional increase in IL-19 serum and degrees of severity of acne vulgaris." (PMID 29805787, 2018). "When all participants (control and acne groups combined) were analyzed together, a statistically significant positive correlation was identified between salivary IL-17 and IL-19 levels (r = 0.672, p < 0.005), as well as between serum IL-17 and IL-19 levels (r = 0.538, p < 0.005)." (PMID 41465543, 2025). "Similarly, two studies found that serum IL-19 levels were significantly higher in acne vulgaris patients compared to the control group, with this increase being proportional to disease severity." (PMID 41465543, 2025). "Furthermore, IL-19 concentrations were found to be proportional to the severity of acne, with the highest levels detected in patients with severe AV (p-value <0.005)." (PMID 38106772, 2023). "Among AV patients, serum IL-19 concentration increased proportionally with the severity of acne, suggesting that IL-19 might serve as an inflammatory marker and could potentially relate to AV." (PMID 38106772, 2023). "Further analysis revealed a significantly higher IL-19 concentration in patients with acne scars." (PMID 38106772, 2023). "Additionally, individuals who had received systemic acne treatment within the last two months exhibited elevated IL-19 levels." (PMID 38106772, 2023). "We further analyzed the IL-19 concentration level among acne groups of different clinical severity levels, based on which we could detect a proportional significant difference between serum concentration of IL-19 and acne severity." (PMID 38106772, 2023). "IL-19 concentration according to the severity of acne and other variables." (PMID 38106772, 2023).
acne (continued). "There are differences in means of IL-19 serum concentration in acne vulgaris patients." (PMID 29805787, 2018). "Moreover, analysis of dependent samples t-test revealed significant difference between IL-19 serum concentration of group of patients with moderate acne vulgaris and that of group of patients with severe acne vulgaris (p = 0.048)." (PMID 29805787, 2018). "Moreover, analysis revealed significant difference between IL-19 serum concentration of group of patients with moderate acne vulgaris and that of group of patients with severe acne vulgaris." (PMID 29805787, 2018). "The significant difference might show that inflammation has a core role in severity of acne vulgaris, and IL-19 might potentially be related to acne vulgaris." (PMID 29805787, 2018). "There are differences in serum levels of IL-19 on the severity of acne vulgaris." (PMID 29805787, 2018). "This may lead to another research to find out that IL-19 might relate more to acne vulgaris inflammation and severity due to its unique features." (PMID 29805787, 2018). "The mean of IL-19 serum concentration of group of patients with mild acne vulgaris is 18.38 ± 9.59 pg/ml, that of group of patients with moderate acne vulgaris is 21.23 ± 11.99 pg/ml, and that of group of patients with severe acne vulgaris is 31.19 ± 20.36 pg/ml." (PMID 29805787, 2018). "The significant difference between IL-19 serum concentration of group of patients with moderate acne vulgaris and patients with severe acne vulgaris might show that inflammation has a core role in severity of acne vulgaris." (PMID 29805787, 2018). "Taken together, CRP, IL-19, and IL-17 display a consistent pattern in our cohort: none showed severity-related systemic elevation despite their known local roles in acne pathophysiology." (PMID 41465543, 2025). "Patients with acne scars exhibited significantly higher concentrations of IL-19 in their sera compared to those without scars." (PMID 38106772, 2023). "This collective profile supports the concept that acne vulgaris involves primarily localized rather than systemic inflammation and that mechanistic interactions between IL-17 and IL-19 may occur at the skin level without substantial systemic reflection." (PMID 41465543, 2025). "There is no study about IL-19 cytokines related to acne vulgaris or acne vulgaris severity." (PMID 29805787, 2018). "In our cohort, neither IL-19 nor CRP demonstrated a severity-related systemic increase, supporting the interpretation that the inflammatory activity in acne vulgaris is predominantly localized rather than strongly systemic." (PMID 41465543, 2025).